IL17F (interleukin 17F)
Diseases named in the same sentence as IL17F in open-access papers (continued):
Sharing a sentence is not in itself a finding about the gene and the disease.
colorectal cancer (6 papers, 2015 to 2024). A primary or metastatic malignant neoplasm that affects the colon or rectum. "Although IL-17A and IL-17F were clarified as risk factors for colorectal cancer during the most recent decades, the concrete reasons were unclear." (PMID 35410225, 2022). "Hence, this meta-analysis was conducted to first explore the association between IL-17A rs2275913 and IL-17F rs763680 polymorphisms and colorectal cancer." (PMID 35410225, 2022). "The IL-17A rs2275913 polymorphism may be an independent risk factor contributing to colorectal cancer susceptibility, while the IL-17F rs763780 polymorphism may decrease susceptibility to colorectal cancer." (PMID 35410225, 2022). "We aimed to examine whether a specific dietary pattern reflecting inflammation was associated with a risk of colorectal cancer and whether IL-17F genetic variant altered this association." (PMID 29874787, 2018). "Our results suggest that polymorphisms in IL17A and IL17F genes may be a predictive source of colorectal cancer therapy type." (PMID 26083022, 2015). "Indeed, the chemotherapy and surgery could reduce the relative risk of colorectal cancer frequency by 31% and 30% respectively in patients with IL17F variant." (PMID 26083022, 2015). "Moreover, this study aims at evaluating the possible interaction between IL17A G197A, IL17F rs763780 and IL23Rrs10889677 polymorphisms as well as the treatment of colorectal cancer in Tunisian population such as the overall survival of patients with and without treatment." (PMID 26083022, 2015). "The expression of β-defensin-1, β-defensin-3, and β-defensin-4 was markedly decreased in IL-17F-knockdown CMT93 cells, demonstrating that IL-17F can promote β-defensin expression in colorectal cancer cells." (PMID 38905308, 2024). "In light of these results, we additionally studied the association between polymorphisms in IL17F, IL17A and IL23R genes and different types of colorectal cancer treatment." (PMID 26083022, 2015). "Previously, we showed that there is a significant association between IL17A, IL17F and IL23R polymorphisms as well as the occurrence of colorectal cancer and the clinical features of the disease." (PMID 26083022, 2015). "The purpose of the present work is to investigate an association between IL17A, IL17F and IL23R polymorphisms in 102 Tunisian patients with colorectal cancer treatment." (PMID 26083022, 2015). "Hereafter, we suggest that IL17A G197A, IL17F rs763780and IL23R rs10889677 polymorphisms are associated with the development and progression of colorectal cancer." (PMID 26083022, 2015). "To verify that IL-17F can promote β-defensin expression, we transfected IL-17F specific small interfering RNA to knock down IL-17F expression in murine colorectal cancer cell line CMT93 and then examined the effects of IL-17F knockdown on β-defensin expression." (PMID 38905308, 2024). "The expression of IL-17F has been investigated most in colorectal cancer (CRC)." (PMID 35012470, 2022). "Recently, we hypothesized that Th17 cells can contribute to carcinogenesis and that IL17A, IL17F and IL23R polymorphisms can affect the susceptibility to colorectal cancer." (PMID 26083022, 2015). "We suggest thatIL17A and IL17F genes may be predictive of colorectal cancer treatment and IL17F may be an independent prognostic factor for an overall survival in colorectal cancer." (PMID 26083022, 2015). "An increasing number of studies and meta-analyses have been performed to explore associations between the IL-17A rs2275913 and IL-17F rs763780 polymorphisms and various types of malignant tumors in recent years; however, the related findings for colorectal cancer display no consensus." (PMID 35410225, 2022). "Here we showed that IL23R variant could increase the susceptibility to colorectal cancer unlike IL17F polymorphism which could confer protection against this cancer." (PMID 26083022, 2015).
colorectal cancer (continued). "Therefore, IL17F may serve as an independent prognostic factor for overall survival in patients with colorectal cancer." (PMID 26083022, 2015). "Canonical pathway analysis has shown effects on the TH2 pathway, IL8 signaling, TREM1 signaling, colorectal cancer metastasis signaling, NFAT in regulation of the immune response, and IL-17F in allergic inflammatory airway diseases." (PMID 30622539, 2018). "Through case / control studies, we have recently showed that unlike IL17F rs763780 and IL23R rs10889677 polymorphisms, IL17A G197A polymorphism is associated with its susceptibility to colorectal cancer." (PMID 26083022, 2015).
systemic lupus erythematosus (6 papers, 2013 to 2024). An autoimmune multi-organ disease typically associated with vasculopathy and autoantibody production. "IL-17F has also been shown to drive renal tissue injury in lupus mice, suggesting the pathogenic functions of IL-17A and IL-17F in lupus pathogenesis." (PMID 34122457, 2021). "Similar to Th17 cells, Tc17 cells secrete IL-17A and IL-17F and are implicated in the pathogenesis of some human autoimmune diseases, such as psoriasis and systemic lupus erythematosus (SLE)." (PMID 24489575, 2013).
tuberculosis (6 papers, 2014 to 2025). A chronic, recurrent infection caused by the bacterium Mycobacterium tuberculosis. "Association between the IL17F rs763780 SNP genotypic variants and clinical parameters of tuberculosis severity." (PMID 31616423, 2019). "We found an association between the IL17F rs763780 SNP and different immunological and clinical parameters related to higher susceptibility to tuberculosis and disease severity, emphasizing the relationship between the SNP and the active form of the infection." (PMID 31616423, 2019). "The aim of this work was to evaluate the existence of a potential association of the non-synonymous variant rs763780 SNP of the IL17F gene with human tuberculosis." (PMID 31616423, 2019). "Overall, we showed that individuals carrying the C allele of the IL17F rs763780 SNP displayed a weaker immune response against Mtb, supporting a potential role for IL17F in tuberculosis." (PMID 31616423, 2019). "Single SNP analysis showed that rs3819024 in IL-17A and rs763780 in IL-17F were significantly associated with the treatment outcomes of tuberculosis." (PMID 27339100, 2016). "Together, our findings identify the IL17F rs763780 SNP as a biomarker of tuberculosis susceptibility and advanced disease severity in Argentina, suggesting that IL17F could be a critical cytokine in tuberculosis immunity." (PMID 31616423, 2019). "Moreover, we analyzed the association of the IL17F rs763780 SNP with tuberculosis disease in Argentina, evaluating the potential relationship of this polymorphism with immunological and clinical parameters of the severity of the disease." (PMID 31616423, 2019). "Furthermore, the logistic regression used to evaluate the association between the IL17F rs763780 SNP and tuberculosis disease was adjusted for age, ethnicity and sex." (PMID 31616423, 2019). "Taken together, our results identify the IL17F rs763780 SNP as a biomarker of tuberculosis susceptibility and disease severity in Argentina, and suggest that IL17F could play a key role in the immune response of the human host to Mtb infection." (PMID 31616423, 2019). "The study also explored SNPs in IL-17A (rs3819024) and IL-17F (rs763780), which were found to have a relationship with tuberculosis prognosis." (PMID 39459627, 2024). "Nevertheless, while the contribution of IL17A to mycobacteria immunity is usually accepted, the role of IL17F in tuberculosis disease has been poorly studied to date." (PMID 31616423, 2019). "Whereas, the contribution of IL17A in immunity to tuberculosis is usually accepted, the role of IL17F has been scarcely studied so far." (PMID 31616423, 2019). "Overall, these results indicate that individuals that mount a more effective immune response against the bacterium secret the highest amounts of IL17F, and suggest that IL17F might have a protective role in human tuberculosis." (PMID 31616423, 2019). "Moreover, we found that SNPs of rs3819024 in IL-17A and rs763780 in IL-17F were weakly related to a prognosis of tuberculosis." (PMID 27339100, 2016). "To further investigate the potential role of IL17F in tuberculosis, we determined the production of this cytokine by PBMCs from HD and TB." (PMID 31616423, 2019). "Our results indicate that IL17A and IL17F may have different roles in the context of tuberculosis." (PMID 31616423, 2019). "Accordingly, whole blood stimulation with specific Mtb antigens showed an increase in the production of IL17F in individuals with latent tuberculosis infection (LTBI) as compared to TB." (PMID 31616423, 2019). "Moreover, we found that SNPs of rs3819024 in IL-17A and rs763780 in IL-17F might be weakly related to the tuberculosis prognosis." (PMID 27339100, 2016). "Strikingly, and in sharp contrast with our reports studying IL17A production, we detected higher levels of IL17F in Mtb-Ag stimulated PBMCs from HD than in TB (p < 0.01), suggesting that these cytokines may play different roles during tuberculosis disease." (PMID 31616423, 2019).
allergic disease (5 papers, 2012 to 2020). An immune response that occurs following re-exposure to an innocuous antigen, and that requires the presence of existing antibodies against that antigen. "This is evident in the accumulation of neutrophils in allergic diseases with high IL-17A and IL-17F production." (PMID 29311948, 2017).
ankylosing spondylitis (5 papers, 2020 to 2021). An autoimmune chronic inflammatory disorder characterized by inflammation in the vertebral joints of the spine and sacroiliac joints. "Recently, dual inhibition of both IL17A and IL17F in the treatment of psoriatic disease and ankylosing spondylitis was shown to be more effective than single inhibition of each cytokine." (PMID 32516406, 2020).
fibrosis (5 papers, 2014 to 2025). the formation of excess fibrous connective tissue in an organ or tissue in a reparative or reactive process. "The frequency of IL-17A and IL-17F distinguish SSc to morphea individuals while dermal expression of IL-17C (low) and IL-17E (high) identifies a fibrosis-specific motif." (PMID 25136988, 2014). "Effects of depletion of Tregs by anti-CD25 administration, and of administration of anti-IFN-γ, anti-IL-17A or anti-IL-17F on fibrosis after three cycles of DSS, were evaluated first by quantification of collagen deposition in mucosa and submucosa by MSB trichrome staining." (PMID 31296924, 2019). "In our study, eight cytokines (CCL21, a T-cell chemoattractant, IL-9, IL-17F, IL-21, IL-28A, I-309, MIP-1β, and TARC) significantly correlated with BDG exposure in those without fibrosis, while only two cytokines (eotaxin-3 and M-CSF) were correlated in those with fibrosis." (PMID 39502781, 2024).
lung carcinoma (5 papers, 2020 to 2024). "Macrophages could synthesize IL-17A and IL-17F, and in turn, IL-17A and IL-17F promoted lung cancer cell growth by macrophages." (PMID 37581321, 2024). "Furthermore, lung carcinogens are highly inflammatory and studies in Tunisia, for example, identified alterations in inflammatory genes- TNF-α, IL8, IL17A, IL17F, CCR2, and VDR Fok1 (rs2228570) and ApaI (rs7975232) that predispose to lung cancer." (PMID 33659210, 2020).
mastitis (5 papers, 2013 to 2022). Inflammation of breast tissue during lactation or postpartum due to an obstructed duct or infection. "In the present study, a total of 12 SNPs were identified in IL-17F and IL-17A genes in Holstein and Inner-Mongolia Sanhe cattle, of which 2 SNPs were arbitrarily chosen for genotyping and further screening to evaluate their potential association with mastitis." (PMID 28101335, 2017). "The production of the signature cytokines IL-17A, IL-17F, and IL-22 in milk over the course of S. uberis, E. coli, and S. aureus mastitis suggest that innate type 3 immunity is part of the natural immunity to mastitis." (PMID 35214754, 2022). "We have shown that Ccl20 is expressed by bovine MEC in response to IL-17A and IL-17F, and Ccl20 has been shown by several groups to be a major response gene of bovine MEC exposed to MAMPs or mastitis-associated bacteria." (PMID 23696826, 2013). "The results indicate that IL-17F and IL-17A could be powerful candidate genes of mastitis resistance and the significant SNPs might be useful genetic markers against mastitis in both dairy and dual purpose cattle." (PMID 28101335, 2017). "The results infer that IL-17A and IL-17F genes could be crucial modifiers of inflammatory diseases and the SNPs might be useful markers of genetic resistance against bovine mastitis development in both dairy and dual purpose cattle." (PMID 28101335, 2017).
pancreatic cancer (5 papers, 2021 to 2025). "IL-17A increases PD-L1 expression through the p65/NRF1/miR-15b-5p axis and promotes resistance to anti-PD-1 therapy, and IL-17F might be associated with a favorable overall survival in pancreatic cancer patients who were treated with gemcitabine." (PMID 37686343, 2023). "As an example, the presence of IL-17F protein in tumor tissue and patient serum has a protective role in oral and pancreatic cancers, whereas it is protumorigenic in prostate and bladder cancers." (PMID 35012470, 2022). "Other studies have also explored the variant form of IL-17F and found it to be a proper antagonist of the anti-angiogenic effects of wild-type IL-17F, and angiogenesis may play a crucial role in the metastasis of pancreatic cancer." (PMID 37686343, 2023). "Furthermore, in pancreatic cancer cells, the citrus fruit bioactive flavonoid apigenin strongly upregulated IL17F (>100-fold) and induced cell death through inhibition of the glycogen synthase kinase-3β (GSK3β)/nuclear factor kappa B (NFKB) signaling pathway." (PMID 36292624, 2022).
pneumonia (5 papers, 2010 to 2022). An acute, acute and chronic, or chronic inflammation focally or diffusely affecting the lung parenchyma, caused by an infection in one or both of the lungs (by bacteria, viruses, fungi, or mycoplasma.). "It simultaneously synergizes with IL-17A and IL-17F to induce antimicrobial peptide expression in epithelial cells and mediate an early mucosal defense response to pneumonia-causing microorganisms in a mouse model." (PMID 36233337, 2022). "In P11, a 32-year-old female patient diagnosed with CVID at the age of 22 and with pneumonias and gastrointestinal symptoms, a novel variant in the interleukin (IL)17F gene, was identified." (PMID 32047491, 2019). "In our CF mice with PA508 pneumonia, E2 increased protein levels in BAL fluid of TNFα and IL-6 (upstream stimulators of IL-17 production) and also increased mRNA levels in lung tissue of IL-23 and the isoforms IL-17A and IL-17F." (PMID 21118573, 2010).
uveitis (5 papers, 2019 to 2025). An inflammatory process affecting a part of or the entire uvea. "Th17 cells have been identified as key players in the inflammatory cascade associated with uveitis, driving the disease’s pathogenesis by releasing pro-inflammatory cytokines such as IL-17, IL-17F, and GM-CSF." (PMID 40072803, 2025). "Inhibition of IL-17A (secukinumab and ixekizumab) alone might increase the risk of uveitis, while simultaneous inhibition of IL-17A and IL-17F (bimekizumab) significantly reduced the risk." (PMID 40621455, 2025). "Inhibition of IL-17A alone might increase the risk of new-onset or recurrent uveitis, but simultaneous inhibition of IL-17A and IL-17F significantly reduced the risk of uveitis." (PMID 40621455, 2025). "In contrast, Bimekizumab, by simultaneously targeting both IL-17A and IL-17F, demonstrates superior uveitis prevention in clinical trials." (PMID 40621455, 2025). "A recent approved drug for axial spondyloarthritis, bimekizumab, a monoclonal antibody that selectively inhibits IL-17A and IL-17F, has showed a lower incidence rate of uveitis among patients randomized to this drug in a pooled analysis from phase 2b/3 trials." (PMID 40084348, 2025). "Therefore, the limitations of Secukinumab and Ixekizumab in preventing uveitis may be related to their inability to block the compensatory effects of IL-17F." (PMID 40621455, 2025). "However, targeting IL-17A in the treatment of uveitis is ineffective, as IL-17A deficiency does not reduce the pathogenicity of Th17 cells in uveitis but rather increases the expression of GM-CSF and IL-17F." (PMID 39076973, 2024). "They found higher levels of IL-1β, IL-4, IL-17A, IL-17F, IL-21, IL-22, IL-31, IFN-γ, sCD40L, and TNF-α, with a significant difference for IL-17F, in BD-recurrent uveitis patients respect to the BD-remitted uveitis group, before drug infusion." (PMID 31134098, 2019).
acne (4 papers, 2014 to 2025). An inflammatory process of the sebaceous glands which is characterized by comedones, nodules, papules and/or pustules on the skin. "Activation of the Th17 cell that induced IL-6 secrete IL-17A and IL-17F which main effector cytokines in acne lesions." (PMID 32380665, 2020). "Our results in two independent groups of acne patients show that the cytokines involved in the differentiation of Th17 cells and the expression of the main effector cytokines IL-17A and IL-17F were significantly expressed in lesions of acne at mRNA and protein level." (PMID 25153527, 2014). "The expression of cytokines IL-6, IL-12p40, INF-γ and TGF-β have not been studied earlier in acne lesions as also noticed by Thiboutot and co-workers, nor cytokines IL-17A, IL-17F, IL-23p19, IL-22 and chemokines CCL20 and CSF2." (PMID 25153527, 2014).
arthropathy (4 papers, 2022 to 2025). Any disorder of the joints. "Despite a lack of association between baseline levels of the IL-23 effector cytokines IL-17A, IL-17F, and IL-22 with joint disease activity in the current analyses, improvements in this domain were observed through 2 years and correlated with baseline levels of acute phase proteins." (PMID 39493888, 2024). "Interestingly, CD4+ and CD8+ T cells in the feet during the acute phase of disease expressed both IL-17A and IL-17F, indicating that IL-17RA signaling may require binding of both IL-17A and IL-17F isoforms in the context of alphavirus-induced arthropathy." (PMID 35143591, 2022). "By contrast, reductions in serum IL-17F, IL-22, and BD-2 levels with guselkumab correlated with improvements in PASI scores across timepoints assessed, but not in joint disease activity." (PMID 39493888, 2024).
atherosclerosis (4 papers, 2013 to 2024). A disease characterized by the build-up of fatty material and calcium deposition in the arterial wall resulting in partial or complete occlusion of the arterial lumen. "Subjects diagnosed with atherosclerosis (p = 0.04) and taking beta-blockers (p = 0.024) had higher levels of IL-17F." (PMID 35277002, 2022).
bladder cancer (4 papers, 2022 to 2025). "In bladder cancer, IL-17F was overexpressed in the cancer group compared with the cystitis and hyperplastic bladder polyp groups." (PMID 35012470, 2022). "The results of a complex study on the immunoreactivity of the ligands and receptors of the IL-17 family in patients with bladder cancer showed significantly elevated IL-17A, IL-17F, and IL-17RC immunoreactivity in the bladder cancer group but decreased IL-17E, IL-17RA, and IL-17RB immunoreactivity." (PMID 37371647, 2023).
chronic obstructive pulmonary disease (4 papers, 2020 to 2024). A chronic and progressive lung disorder characterized by the loss of elasticity of the bronchial tree and the air sacs, destruction of the air sacs wall, thickening of the bronchial wall, and mucous accumulation in the bronchial tree. "Different IL-17 proteins are linked to distinct biological activities i.e. IL-17A is associated with chronic obstructive pulmonary disease (COPD), while IL-17F in psoriasis and rheumatoid arthritis." (PMID 38983855, 2024).